BCL2 (BCL2 apoptosis regulator)
Diseases named in the same sentence as BCL2 in open-access papers (continued):
Sharing a sentence is not in itself a finding about the gene and the disease.
lung carcinoma (continued). "Kaempferol induced apoptosis in lung cancer A549 cells by inactivating AKT1, downregulating the expression levels of Bcl-2 and Bcl-xL, upregulating the expression levels of Bax, and cleaving PARP." (PMID 38606171, 2024). "CREB activation upregulates the expression of TIPRL, Bcl2, and HMG20A to maintain the stemness and survival of CSCs, thus promoting tumorigenesis in lung cancer." (PMID 39076120, 2024). "In turn, the activated CREB upregulates the expression of TIPRL, Bcl2, and HMG20A to maintain the stemness and survival of CSCs, thus promoting tumorigenesis in lung cancer." (PMID 39076120, 2024). "It increases levels of Bax, cleaved Caspase-3, -8 and-9, and decreases Bcl-2 in CL1-5 and H520 cells, effectively inducing lung cancer cell death through the mitochondria-dependent apoptosis pathway." (PMID 38628670, 2024). "TIPRL depletion significantly reduced the mRNA and protein levels of Bcl2 and HMG20A, among various potential target genes, in several lung cancer cell lines." (PMID 39076120, 2024). "Antisense oligonucleotides: Lipid nanoparticles loaded with a gapmer antisense oligonucleotide against Bcl-2 (G3139-GAP) were developed to deliver a modified antisense oligonucleotide targeting the Bcl-2 gene, crucial for lung cancer treatment." (PMID 38794306, 2024). "B-cell lymphoma 2 (BCL-2) and myeloid cell leukemia 1 (MCL-1), the pro-survival members of BCL-2 family proteins, are upregulated in lung cancer cells and play a critical role in evading apoptosis and drug resistance." (PMID 38666017, 2024). "Our results revealed consistently significant high levels of the pro-survival protein BcL-2 in CASD1 knockout cells compared to the wild type and SIAE knockout cell lines for the lung cancers and wild type for the colon cancers." (PMID 37377914, 2023). "Except for the co-administration of PERI with the dual BCL-2 and BCL-xL inhibitor navitoclax in lung cancer cell lines, there are hardly any data on combinatorial approaches." (PMID 36674872, 2023). "According to the result of qRT-PCR, the expression of hTERT and BCL-2 genes decreased significantly, while the expression of BAX increased in the treated A549 lung cancer cells." (PMID 37664043, 2023). "For instance, a search for chemokine/chemokine receptor system in lung cancer showed that the interaction of CC-chemokine ligand 21 (CCL21) with its receptor CC-chemokine receptor 7 (CCR7) may help protect against tumor cell apoptosis through p-ERK-mediated increase of the Bcl-2/Bax ratio." (PMID 38031087, 2023). "DH_32 was capable of inducing apoptosis in lung cancer cells, as demonstrated by increased PARP cleavage and reduced levels of the proapoptotic protein Bcl2." (PMID 38132948, 2023). "enhanced chemopreventive potential against development of lung carcinogenesis by stimulating the apoptotic machinery.decreased BCL-2 expression and improved BAX protein expression in lung cancer cells." (PMID 36926328, 2023). "In A549 and H460 lung cancer cells, cardamonin was reported to inhibit the PI3K/Akt pathway and increase the expression of caspase-3, Bcl-2, and Bax at a concentration of 40 μM." (PMID 37568796, 2023). "The overexpression of the miR-200bc/429 cluster increases cisplatin-induced apoptosis by repressing the expression of Bcl-2 and XIAP in lung cancer cells." (PMID 36778005, 2023).
lung carcinoma (continued). "Last, we proposed a therapeutic option for tuft cell-like lung cancers, i.e., co-inhibition of PARP and BCL2." (PMID 36402755, 2022). "Our data showed that PRDX5 knockdown and PAM treatment induced ROS generation, downregulated the anti-apoptotic protein BCL2, disrupted the MMP, and enhanced apoptosis in A549 lung cancer cells." (PMID 35546738, 2022). "Here, we report that overexpression of the RUNX2 gene in lung cancer may be related to the inhibition of the intrinsic apoptosis pathway, specifically, through direct transcriptional regulation of the antiapoptotic gene BCL2 and indirect regulation of BCL-XL and MCL1." (PMID 36510562, 2022). "Indeed, therapeutic approaches using down-regulation of bcl2 might be useful in lung cancer." (PMID 33773561, 2021). "Induction of apoptosis on lung cancer cells by MS13 treatment was further determined by caspase-3 activity and Bcl-2 protein concentration level." (PMID 34299042, 2021). "We found that patients with mRNA BCL2 high expression had a better prognosis than low expression in TCGA LUAD, TCGA lung cancer, GSE37745, and GSE37745 cohorts (P < 0.05)." (PMID 34408984, 2021). "Of note, inhibition of Bcl-2 and Bcl-xL by BH3-mimetic ABT-263 enhanced the sensitivity of HCT116 colon cancer and NCI-H460 lung cancer cells to the cytotoxic action of ionizing radiation." (PMID 34257274, 2021). "In summary, we demonstrated that exposure to acute or cycling hypoxia changed the Bcl-2 rheostat and increased resistance to radiotherapy in NCI-H460 lung cancer and HCT116 colon cancer cells." (PMID 34257274, 2021). "Data analysis demonstrated increased Bax protein levels in lung cancer cell lines compared to MRC5, whereas decreased Bcl2 protein levels in lung cancer cell lines compared to MRC5 cells were observed." (PMID 34952904, 2021). "By targeting AKT, HDAC10 affects the expression of B-cell lymphoma-2 (BCL2) as well as BCL2 antagonist/killer (BAK), which induces apoptosis in lung carcinoma." (PMID 33997894, 2021). "In the present study, morphological analysis and biochemical assays such as caspase 3 and bcl-2 were performed to determine the effect of MS13 on induction of apoptosis in NCI-H520 and NCI-H23 lung cancer cells." (PMID 34299042, 2021). "JNK is a proapoptotic protein kinase that leads to the inhibition of antiapoptotic BCL-2 proteins by phosphorylating them and, thus, inducing cell death in HEK 293T, lung cancer (A549) cells, hepatocytes, and beta-cells." (PMID 34571827, 2021). "In lung cancer cells A549, GSP significantly increased the expression of p-JNK, p-P38 protein before and after ionizing radiation, and the value of Bax/Bcl-2 after irradiation, and had less effect on p-ERK protein." (PMID 33854585, 2021). "In bladder and lung cancer, inhibition of PI3K/Akt/mTOR significantly inhibits migration and tumorigenesis while increasing apoptosis via downregulation of Bcl-2 proteins." (PMID 34316328, 2021). "In vitro, leptin significantly increased the viability of lung cancer cell lines A549 and H460 in a dose-dependent manner by activation of STAT3, Bcl-2, and cyclin D1." (PMID 33708630, 2021). "To generalize the role of bcl-2 on TAM functions, we evaluated the effects of CM derived from H1299 lung cancer cells." (PMID 32269145, 2020).
lung carcinoma (continued). "Here, we identified the activity of the ‘IL2 signaling events mediated by STAT5’ pathway as a robust biomarker for the response to two highly similar Bcl-2 protein–family inhibitors (ABT-263 and ABT-737) in lung cancer cell lines." (PMID 32620799, 2020). "The expression of XIST and co-regulated genes TSIX, hnRNPu, Bcl-2, and BRCA1 analyses in lung cancer (LC) and controls were performed in silico." (PMID 33255394, 2020). "In lung cancer, OIP5-AS1 targets miR-448 and Bcl-2 to regulate the proliferation and apoptosis of cancer cells." (PMID 33092644, 2020). "Leveraging the available large-scale sequence data from TCGA and GTEX, we demonstrate that XIST, TSIX, hnRNPu, Bcl-2, and BRCA1 are differentially expressed in two different types of lung cancer when compared to controls." (PMID 33255394, 2020). "In vitro anti-lung cancer studies revealed that SC, SCA, SCH, and SCAH decreased MMP, decreased Bcl-2 expression, increased the release of cytochrome c, increased activation of caspase-9 and -3, and increased late apoptosis of A-549 cells." (PMID 32604764, 2020). "Consistently, we found borderline positive correlation between Bcl-2 and PRDM10 expression in breast, colon, and lung cancers." (PMID 31143550, 2019). "In addition, the expression of C-MYC, Cyclin D1, Bcl-2, Bcl-xL, COX-2, TWIST1, and MMP2, which are associated with NF-κB signaling, was analyzed to better understand the NF-κB pathways involved in inhibiting lung cancers and was obviously decreased by 160 μM EGCG." (PMID 31777584, 2019). "Previous study showed that BCL-2 inhibitor Venetoclax and navitoclax enhanced apoptosis in vitro and reduced tumor propagation or burden in BCL-2–expressing lung cancer cells induced animals in vivo." (PMID 31450709, 2019). "Our data suggest the oncogenic function of the novel fusion gene VAPA-Rab31 via upregulated Bcl-2 and activated CREB in lung cancer." (PMID 31083279, 2019). "Down-regulation of caveolin-1, Mcl-1 and Bcl-2 as well as suppression on AKT and ERK activation successfully initiate detachment-induced cell death in anoikis-resistant lung cancer cells." (PMID 29631569, 2018). "Here, we demonstrated that in lung cancer cell lines, econazole promote apoptosis through inhibiting the activity of PI3Kα via AKT and Bcl2." (PMID 29269744, 2017). "In the present study, we observed induction of apoptosis in honokiol-treated KRAS mutant lung cancer cells, which was supported by an increased amount of cleaved PARP and pro-apoptotic proteins Bax, with a reduction of anti-apoptotic Bcl-2 protein." (PMID 28443025, 2017). "In this regard, the decreased expression of Bcl-2 and upregulation of Bax confirms that BGT also affects the survival mechanism of lung cancer A549 cells." (PMID 28611451, 2017). "In lung cancer cells transfected with RBM5, pro-apoptotic protein Bax was increased while anti-apoptotic protein Bcl-2 was decreased reversely." (PMID 28061901, 2017). "Previous studies of JFK demonstrated that JFK induced lung cancer cell death by regulating some apoptotic gene expression, such as AIFM2, IL-2, and Bcl2." (PMID 29234412, 2017). "Further investigation showed the down-regulation of B-cell lymphoma 2 (Bcl-2), up-regulation of Bcl-2 homologous antagonist/killer (Bak), and nuclear translocation of apoptosis-inducing factor (AIF) in montelukast-treated lung cancer cells." (PMID 28672809, 2017).
lung carcinoma (continued). "We here provided evidence to support the previous report, indicating that a decrease in miR-184 by E6 oncoprotein confers cisplatin resistance in lung cancer cells and unfavorable chemotherapeutic response in NSCLC patients due to increasing Bcl-2 expression." (PMID 27083050, 2016). "As observed in lung cancer model, co-immunoprecipitation of bcl-2-fused protein and SLIRP was observed in IM prepared from total extract of MDA-MB-231 FLAG-bcl-2." (PMID 26866271, 2016). "While EGFR emerged as the most interesting candidate, other genes with intriguing connections to lung cancer biology, including HMGA2, BCL2, and others, will be the focus of future studies." (PMID 26556242, 2015). "Here, we reported that miR-206 is indeed suppressed in primary lung cancers compared with the matching normal tissues, and found 3′-UTR of the human MET and BCL2 mRNA are really targets of miR-206." (PMID 26325180, 2015). "G31P also enhanced apoptosis in lung cancer cells as determined by elevated levels of cleaved PARP, Caspase-8, and Bax, together with a reduced expression of the anti-apoptotic protein Bcl-2." (PMID 26087179, 2015). "Bcl-2 and Bcl-xl expression are mainly regulated by STAT3 pathway, and these proteins are overexpressed in lung cancer cells." (PMID 25788267, 2015). "Since curcumin induced mitochondria-mediated apoptosis as evidenced by the release of cytochrome C in the cytoplasm, we next examined the expression of Bcl-2 in both SCCHN and lung cancer cell lines." (PMID 25910231, 2015). "The enhanced expression of miR-200bc/429 cluster resulting decrease of BCL-2 and XIAP protein, which make the gastric SGC7901/VCR and lung cancer A549/CDDP became sensitive to VCR/CDDP induced apoptosis." (PMID 25342041, 2014). "Herein, we report our evaluation of FA deficiency in a series of tumors from patients with NSCLC and the response of lung cancer cells with reduced FANCD2 expression (FANCD2 knock-down cell) to treatment with inhibitors of PARP, CHK1, and BCL-2/XL." (PMID 25566506, 2014). "The BBR-SD produced 2.37 fold higher repression in the Bcl-2 expression compared to BBR free drug, suggesting the superior anticancer effects of BBR-SD in lung cancer." (PMID 24614362, 2014). "Expression of Bcl-2, cleaved caspase-3, caspase-9 and PAPP proteins in A549 lung cancer cells and the A549 xenograft BALB/c nude mice model was determined by Western blot." (PMID 22866867, 2012). "The BCL-2 antagonist ABT-263 efficiently suppresses B-cell lymphoma and lung cancer cells." (PMID 40392781, 2025). "DMC induces apoptosis in lung cancer (A549) and bladder cancer (RT4 and TCCSUP) cells by activating Caspase-3 and Caspase-9 activity, and inhibiting the expression of anti-apoptotic proteins (Bcl-2 and Bcl-xL)." (PMID 40490812, 2025). "Overexpressed BCL-2 and MCL-1 have been recognized for various types of lung cancer cells." (PMID 38666017, 2024). "Additionally, GX15-070, a pan inhibitor of MCL1, BCL2, BCLXL, BCLW, and BFL1, has been shown to induce cell death in Tregs and enhance clearance of lung cancer cells when combined with a rV/F-CEA-TRICOM vaccine." (PMID 38459020, 2024). "The authors suggest that the use of GAL may enhance cisplatin-based therapies in treatment-resistant lung cancer cells by inactivating the p-STAT3/p65 and Bcl-2 pathways." (PMID 38674891, 2024). "Lung cancer induction considerably activated BCl2 gene expression by about 40% compared to the negative control (p ≤ 0.05)." (PMID 39338293, 2024).
lung carcinoma (continued). "SFP induces apoptosis in lung cancer cells by triggering cell cycle arrest in the S phase and modulating the activities of the proteins Bcl-2 and Bax, without visible damage to either healthy animals or normal lung cells." (PMID 37239989, 2023). "Also, natural products (NP) activate apoptotic pathways in lung cancer cell including p‐JNK, Akt/mTOR, PI3/ AKT\ and Bax, Bcl2, but suppressed AXL phosphorylation." (PMID 37697969, 2023). "Also, immunoblot studies revealed quercetin, and curcumin-treated lung of mice significantly decreased BCL-2 expression and improved BAX protein expression in lung cancer cells." (PMID 36926328, 2023). "Regarding the anticancer effect of MET and SIL, in this research, we investigate the synergistic effect of co-delivery MET and SIL loaded in PEGylated niosome to enhance their bioavailability and evaluate their effects on the expression of hTERT, BCL-2, and BAX genes in NSCLC type lung cancer cells." (PMID 37664043, 2023). "And, in a more recent study, breast and lung cancer cells resistant to shear stress revealed an up-regulation of DSC2 and PKP1, leading to more CTC cluster formation and enhanced cell survival in circulation via activation of the PI3K/AKT/Bcl-2 pathway." (PMID 36927383, 2023). "WB protein level detection further verified that the expression levels of lung cancer cell proliferation–related proteins PCNA and KI67 and anti-apoptotic protein Bcl-2 were significantly decreased after adding Exos, but the expression of pro-apoptotic protein Bax was increased." (PMID 36643646, 2023). "In this study, we revealed that ZQT played an immunomodulatory role in an orthotopic lung cancer mouse model via reducing the population of G-MDSCs and inhibiting their immunosuppressive activity in TME by activating the STAT3/Bcl-2/caspase-3 signaling pathway." (PMID 33867859, 2021). "Meanwhile, the lung cancer patients treated with radiotherapy had poorer survival in Bcl-2 overexpressing group than patients without Bcl-2 expression." (PMID 34604239, 2021). "Furthermore, we found increased mRNA of PIK3CB, PIK3CD, PIK3CG, BCL2, TUBB3 in ALK-positive lung cancer, which suggested activation of PI3K/AKT signaling pathway." (PMID 34234236, 2021). "Studies have shown that ICT (MOL056) could act on the PI3K-AKT signaling pathway to down-regulate the expression of Bcl-2 and up-regulate Bax, which promotes the apoptosis of lung cancer cells in the TME, thereby achieving the purpose of treating lung cancer." (PMID 33460401, 2021). "Furthermore, it induces the detachment and apoptosis of A549 human lung cancer cells, inhibits tumor cell growth in hepatocarcinoma, promotes TNF-α and IFN-γ expression, increases the Bax/Bcl-2 ratio, and activates caspases-3 to induce apoptosis." (PMID 33673020, 2021). "TOB1 could inhibit the proliferation and metastasis of lung cancer cells through a series of downstream regulators, including cyclin D1, AKT signal transduction, BCL-2, BCL-XL, and SMAD4." (PMID 34604392, 2021). "Finally, to evaluate the clinical potential of combined harmine and Bcl-2 antagonist therapy, we established four primary NSCLC cancer cell lines from lung cancer patients." (PMID 32587776, 2020). "The result shows miR-216b introduction downregulates Smad3, increases BCL-2 level, induces chemoresistance to carboplatin with an increase in IC50, and decreases apoptosis, indicating that miR-216b is a potential upstream regulator of BCL-2 in lung cancer." (PMID 32668597, 2020).